RNU6-858P (RNA, U6 small nuclear 858, pseudogene)
Gene: Small nuclear RNA gene on chromosome 3 (197,894,507 to 197,894,613, forward strand). Ensembl gene ENSG00000199306.
Homologues: Orthologues: macaque U6 (95% identical), chimpanzee U6 (85% identical), pig U6 (77% identical), guinea pig U6 (70% identical), dog U6 (65% identical). Paralogues in human: RNU6-1060P (88% identical), RNU6-15P (88% identical), RNU6-33P (87% identical), RNU6-463P (87% identical), RNU6-1 (86% identical), RNU6-116P (86% identical), RNU6-1263P (86% identical), RNU6-2 (86% identical), RNU6-329P (86% identical), RNU6-3P (86% identical), RNU6-48P (86% identical), RNU6-4P (86% identical), and 1286 more.